TGFBR1 (transforming growth factor beta receptor 1)
Diseases named in the same sentence as TGFBR1 in open-access papers (continued):
Sharing a sentence is not in itself a finding about the gene and the disease.
Marfan syndrome (31 papers, 2007 to 2025). A disorder of the connective tissue. "While FBN1 mutations are the main cause, other genes have been implicated in Marfan syndrome and Marfan-like conditions, including TGFBR1 and TGFBR2." (PMID 41411243, 2025). "We compared clinical manifestations and outcomes both between the Loeys-Dietz syndrome versus Marfan syndrome groups, and within the Loeys-Dietz syndrome group according to the pathogenic variant in the TGFBR1, TGFBR2, and SMAD3 gene." (PMID 31795342, 2019). "In seven individuals, comprising two individuals with TGFBR1 pathogenic variant, and five with Marfan syndrome, proximal aortic surgery was extended into the arch." (PMID 31795342, 2019). "The 2017 ESC guideline states that surgery is indicated in all patients with Marfan syndrome and a maximal aortic diameter ≥ 50 mm, and that in patients with additional risk factors and in patients with a TGFBR1 or TGFBR2 mutations surgery should be considered at a maximal aortic diameter ≥ 45 mm9." (PMID 36097197, 2022). "We obtained a molecular diagnosis in 45/53 (85%) index patients, in which 36/53 (68%) had rare variants in FBN1 (Marfan syndrome; 63 patients in total), seven (13.3%) in TGFBR1/TGFBR2 (Loeys–Dietz syndrome; nine patients in total) and two patients (3.7%) in SKI (Shprintzen–Goldberg syndrome)." (PMID 33436942, 2021). "Furthermore, the top five diseases with a high score of TGFBR1-skeletal system disease association were craniosynostosis, connective tissue disease, Marfan syndrome, isolated brachycephaly, and isolated scaphocephaly." (PMID 32582282, 2020). "Mutations in genes encoding TGFBR1/2 and SMAD3 are implicated in patients with SCAD and fibromuscular dysplasia (TGF-β), Ehlers–Danlos syndrome (TGF-β1, and TGF-β2 in type IV), Loeys–Dietz syndrome (SMAD2/3, TGFBR1/2), and Marfan syndrome." (PMID 39595023, 2024). "In this category of patients, aortic dilatation andresulting complications develop from intrinsic molecular genetic alterations ofthe FBN1 gene in Marfan syndrome or the TGFBR1 orTGFBR2 genes in LDS." (PMID 39077175, 2022). "For example, genetic variants in transforming growth factor beta (TGF-β) receptors type 1 (TGFBR1) and type 2 (TGFBR2) genes are commonly found in Marfan syndrome and can also be associated with patent ductus arteriosus and VSDs." (PMID 30257432, 2018). "Historically, the understanding of heritable TAAD was anchored in syndromic disorders such as Marfan syndrome (caused by pathogenic FBN1 variants) and LDS (linked to TGFBR1, TGFBR2, SMAD3, SMAD2, TGFB2, and TGFB3), conditions defined by clear Mendelian inheritance patterns and systemic features." (PMID 40981152, 2025). "In humans, heterozygous variants in TGFBR1 have been associated with a rare genetic disorder known as Loeys–Dietz syndrome (LDS), which shares overlapping, but distinct phenotypic characteristics with Marfan syndrome." (PMID 37998513, 2023). "Marfan syndrome (MFS) is associated with FBN1 mutations; Ehlers–Danlos syndrome (EDS) is relevant to the COL3A1 mutation; Loeysؘ–Dietz syndrome (LDS) is related to TGFBR1 or TGFBR2 mutations as well as SMAD3 or TGFB2 mutations." (PMID 36291545, 2022). "Mutations underlying classic Marfan syndrome involve the FBN1 gene, whereas mutations in TGFBR1 and 2, SMAD2 and 3, and TGFB2 and 3 can be detected in Loeys-Dietz syndrome types 1 to 6, and a Col3A1 gene mutation has been described for the vascular type of EDS2,3." (PMID 36097197, 2022). "Historically, genetic testing focused on core syndromic genes, such as FBN1, TGFBR1/2, and COL3A1, which collectively account for the majority of diagnoses in classic connective tissue disorders like Marfan syndrome, LDS, and vEDS." (PMID 40981152, 2025). "Causative genes include autosomal polycystic kidney disease (PKD1, PKD2), Ehlers–Danlos syndrome (COL3A1), Marfan syndrome (FBN1), Loeys–Dietz syndrome (TGFB2, TGFB3, TGFBR1, TGFBR2, SMAD2, SMAD3), and Majewski Osteodysplastic Primordial Dwarfism (PCNT)." (PMID 40004483, 2025).
Marfan syndrome (continued). "A more comprehensive understanding of the disease would require detailed genetic characterization beyond FBN1, including TGFB2, its receptors (TGFBR1, TGFBR2), and other genes involved in Marfan syndrome and related disorders." (PMID 40243722, 2025). "The best characterized genes include FBN1 [Marfan syndrome (MFS)], TGFBR1 and TGFBR2 [Loeys-Dietz syndrome (LDS)], SMAD3 [aneurysm-osteoarthritis syndrome (AOS)], and ACTA2 [Aortic and Cerebral Aneurysm (ACA)]." (PMID 36312254, 2022). "Therefore, our objective was to assess the mRNA expression of FBN1, TGFBR1, TGFBR2, and TGFB2 in the aortic tissue of Marfan syndrome patients with aortic dilation." (PMID 40243722, 2025).
prostate carcinoma (28 papers, 2004 to 2026). A carcinoma that arises from epithelial cells of the prostate gland. "We applied comprehensive genotyping for TGFB1 and TGFBR1 polymorphisms in relation to acute and late side effects of radiotherapy in prostate cancer." (PMID 34771749, 2021). "Our results suggest that the association between TGFBR1*6A and prostate cancer is at best very weak but further studies are needed to formally exclude an association with early onset prostate cancer." (PMID 15385056, 2004). "To examine the possibility that TGFBR1*6A is associated with early onset prostate cancer, we determined the prostate cancer risk for individuals above and below the age of 55." (PMID 15385056, 2004). "The association between carrier status of TGFBR1*6A and prostate cancer in younger age group was significant after adjustment for race (OR 2.13, 95% CI 1.06–4.27) but was not significant after adjustment for race and age strata within groups (OR 2.11, 95% CI 0.98–4.57)." (PMID 15385056, 2004). "We investigated 40 germline polymorphisms in peripheral blood cells, covering the entire common genetic variability in the TGFβ1 ligand (gene TGFB1) and the TGFβ receptor-1 (TGFBR1) in 240 patients treated with primary radiotherapy for prostate cancer." (PMID 34771749, 2021). "Via comprehensive genotyping of TGFB1 and TGFBR1, promising biomarkers for radiotoxicity in prostate cancer were identified." (PMID 34771749, 2021). "As shown, TGFBR1 mRNA in thyroid, lung, pancreas, colon, and prostate cancer tissues displayed higher levels than in the matched normal tissues." (PMID 32582282, 2020). "Downregulation or loss of TGF-β receptors was observed in about 30% of cases of prostate cancer compared with normal prostate tissues while expressions of TGFBR1 and TGFBR2 were lower in metastatic compared with primary tumors." (PMID 31842336, 2019). "Knock-out of Tgfbr1 in mice inhibits bone metastases of prostate cancer cells by disrupting their interactions with the bone microenvironment." (PMID 31842336, 2019). "A loss of expression of TGFBR1 and CYR61 has been associated with prostate cancer progression and/or recurrence among many other cancer types." (PMID 24466240, 2014). "Among younger patients with prostate cancer we found that 13 of 59 were TGFBR1*6A carriers yielding an allelic frequency of 0.119, one of the highest TGFBR1*6A allelic frequency ever reported." (PMID 15385056, 2004). "The intriguing findings of a high TGFBR1*6A allelic frequency among prostate cancer cases diagnosed before the age of 55 have to be cautiously interpreted given the fact that this group only included 46 patients." (PMID 15385056, 2004). "Furthermore, in prostate cancer patients TGFBR1 expression was highly correlated with mitotic spindle and G2/M checkpoint." (PMID 35853811, 2022). "Moreover, expression of TGFBR1 was strongly correlated with mitotic spindle and G2/M checkpoint gene sets in prostate cancer." (PMID 35853811, 2022). "To test the hypothesis that TGFBR1*6A may contribute to the development of prostate cancer, we conducted a case control study of patients with biopsy verified prostate cancer cases and geographically and ethnic-status matched controls." (PMID 15385056, 2004). "While there is growing evidence that TGFBR1*6A predisposes to the development of breast, colon and ovarian cancer, our data do not suggest that it predisposes to the development of prostate cancer." (PMID 15385056, 2004). "A total of 907 cases and controls from New York City were genotyped to test the hypothesis that TGFBR1*6A may contribute to the development of prostate cancer." (PMID 15385056, 2004). "The present study has the power to detect an O.R. for prostate cancer of 1.70 or higher and therefore rules out a major association between TGFBR1*6A and prostate cancer." (PMID 15385056, 2004).
prostate carcinoma (continued). "An extensive study launched to test formerly reported associations of candidate gene markers (including TGFB1, but not TGFBR1) for impact on early or late side effects of radiotherapy in breast and prostate cancer did not prove a statistically significant risk for any of the markers tested." (PMID 34771749, 2021). "If the TGFBR1*6A allele predisposes to a lethal malignancy such as prostate cancer, however, its frequency could be higher, not lower, in a younger cohort." (PMID 15385056, 2004). "BMPs are a diverse class of growth factor proteins that belong to the transforming growth factor-β (TGFB1, TGFB2, TGFBR1, TGFBR2) superfamily, and aberrant expression of various BMPs has been reported in several tumor tissues, including prostate cancer." (PMID 40596459, 2025). "Decreased expression of miR-133b in prostate tumors and bone metastases leads to upregulation of TGFBR1 and TGFBR2, enabling TGF-β signaling, which contributes to the migration and invasion of prostate cancer cells." (PMID 31842336, 2019). "Notably, PP2A inhibits TGFβ signaling by TGFBR1 dephosphorylation, and downregulation of PP2A in prostate cancer leads to enhanced TGFβ signaling." (PMID 38474330, 2024). "Our data suggest that TGFBR1*6A does not contribute to the development of prostate cancer." (PMID 15385056, 2004).
hepatocellular carcinoma (27 papers, 2009 to 2025). A malignant tumor that arises from hepatocytes. "In contrast, microRNA-140-5p suppresses tumor growth and metastasis by targeting TGFBR1 in hepatocellular carcinoma." (PMID 27409174, 2016). "A comparative analysis of miR-122 interactors in different pathways describes the presence of several genes associated with CRC including SMAD4, TGFBR1, AKT, MYC, Rho, Ras, Raf, Bax, and CDK 4/6 to actively engage in hepatocellular carcinoma and other pathways of cancer." (PMID 36499586, 2022). "In order to examine whether let-7c may directly regulate TGFBR1 expression, we overexpressed let-7c miRNA in the hepatocellular carcinoma HuH7 cells, and measured the expression of TGFBR1 mRNA and protein." (PMID 19841744, 2009). "In addition, exosomal circGSE1 secreted by hepatocellular carcinoma cells (HCC) can induce the expansion of Treg cells by regulating the miR-324-5p/TGFBR1/Smad3 pathway, which promotes the secretion of immunosuppressive factors, inhibits the function of CD8+ T cells, and causes tumor immune escape." (PMID 38633106, 2024). "Exosomal circ-GSE1 promoteS immune escape of hepatocellular carcinoma (HCC) by inducing the expansion of regulatory T cells via the regulation of miR-324-5p/TGFBR1/Smad3/Tregs axis." (PMID 37525158, 2023). "The known mRNA interactors of miR-122 include PKM2, AKT1, MYC, TGFBR1, and SMAD4 in hepatocellular carcinoma, JNK, AP1, and caspases 3/8 in irritable bowel disease, and AKT, PI3K, PCNA, MTDH, PI3K, TRIM29, Bcl-W, CCNG1, and ALDO2 in CRC." (PMID 36499586, 2022). "LncRNA AK002107 and SBF2-AS1 both target Transforming Growth Factor Beta Receptor 1 (TGFBR1) by sponging miR-140-5p, thereby promoting migration and invasion of hepatoma cells." (PMID 34758879, 2021). "miR-140-5p also plays a tumor suppressor role in hepatocellular carcinoma by controlling NF-κB activity by directly regulating DNMT1 expression, and suppresses tumor growth and metastasis by targeting TGFBR1 and FGF9." (PMID 27588393, 2016).
glioma (26 papers, 2011 to 2025). A benign or malignant brain and spinal cord tumor that arises from glial cells (astrocytes, oligodendrocytes, ependymal cells). "From these analyses, we demonstrated a viable clinical strategy in combination with TGFB1/TGFBR1 inhibitors and PD-1/PD-L1 inhibitors for the treatment of high-risk gliomas." (PMID 36778912, 2022). "Consistently, lower expression levels of AKT2and TGFBR1 were detected in higher grade gliomas compared to other types of brain tumours, which was inverse tothe level of expression detected for the heparin-binding EGF-like growth factor (HBEGF) gene." (PMID 34455717, 2021). "In our study, we observed that TGFBR2 expression was higher in the glioma cell line than TGFBR1 and TGFBR3." (PMID 33576874, 2021). "However, our study focused on uncovering the role of PSMB8-mediated malignant glioma phenotypes through the activation of the TGFBR1/2-SMAD2/3 axis." (PMID 40335825, 2025). "Finally, SMURF2Thr249 phosphorylation was negatively correlated with the TGFBR1 protein levels in human glioma specimens." (PMID 35017630, 2022). "miR-142-3p is downregulated in glioblastoma-infiltrating macrophages, which contribute to the glioma growth probably by promoting M2-like TAM apoptosis through targeting transforming growth factor beta receptor 1 (TGFBR1) and transforming growth factor beta 2 (TGFB2)." (PMID 29899293, 2018). "This suggested that TGFB1/TGFBR1 inhibitors may be sensitive in gliomas." (PMID 36778912, 2022). "After silencing PSMB8, reduced expression of TGFBR1 and TGFBR2 led to decreased phosphorylation of SMAD2/3, which inhibited the malignant behavior of glioma cells." (PMID 40335825, 2025). "Then, we selected the top 5 relevant immunomodulators, including an immunostimulator (CD276), two immunoinhibitors (IL10RB and TGFBR1), a chemokine (CXCL10) and an MHC (HLA-A), in the glioma dataset and drew scatterplots to show their details." (PMID 37006287, 2023). "For instance, galunisertib, an inhibitor of TGFBR1, blocks the function TGF-β signalling and enhances the anti-tumour effects of CD133 and Her2 chimeric antigen receptor (CAR) T cells against both glioma and breast cancer." (PMID 33114183, 2020). "Meanwhile, we found that the phosphorylated levels of TGFBR1, Smad2 and Smad3 and the nuclear levels of Smad2/Smad3 were markedly increased in the SMC4-overexpressing glioma cells but decreased in the SMC4-silenced cells." (PMID 28287612, 2017). "By analyzing the main signaling pathways that induce the EMT phenotype, we found that TGF-β was the most important one in gliomas, and TGFB1/TGFBR1 showed stronger immunosuppressive properties than PD-L1 and CTLA-4, especially in inducing an increase in CD8+ T cytopenia and M2 macrophages." (PMID 36778912, 2022). "Moreover, SD-208, a novel inhibitor of TGFBR1, induces the infiltration of immune cells, including macrophages, CD8+ T cells, and NK cells, to enhance the immunogenicity of glioma cells and inhibit tumour progression." (PMID 33114183, 2020).
renal fibrosis (25 papers, 2018 to 2026). A final common manifestation of a wide variety of chronic kidney diseases characterized by glomerulosclerosis and tubulointerstitial fibrosis. "Inhibiting pro-inflammatory cytokines and factors associated with renal fibrosis in human renal glomerular endothelial cells.Attenuating LN by targeting transforming growth factor beta receptor 1 (Tgfbr1), an enhancer of the TGF-β/Smad/TLR3 pathway." (PMID 39835138, 2024). "Let-7b has also been reported to regulate renal fibrosis in proximal tubular cells and mesangial cells via regulation of TGFBR1 under renal injury." (PMID 31979395, 2020). "In order to explore the mechanism of miR-140-5p in the pathogenesis of renal fibrosis, we identified that TGFBR1 is a direct target of miR-140-5p in humans and mice." (PMID 33013464, 2020). "In summary, these results suggested that miR-140-5p may inhibit renal fibrosis by targeting the TGFBR1-mediated TGF-β1/smad signaling pathway." (PMID 33013464, 2020). "Overall, our results suggested that miR-140-5p may protect the HK2 cells from TGF-β-induced renal fibrosis by directly targeting TGFBR1." (PMID 33013464, 2020). "Among the predicted targets, we found that TGFBR1 may be a functional target gene of miR-140-5p for renal fibrosis because it plays a key role in mediating the TGF-β1 signal pathway." (PMID 33013464, 2020). "However, the role of TGFBR1 in renal fibrosis was still poorly studied." (PMID 33013464, 2020). "Long noncoding RNA (lnc-TSI) blocked the interaction of Smad3 with TGFBR1 by binding with the MH2 domain of Smad3 and attenuated renal fibrosis." (PMID 35680856, 2022). "Inhibit the expression of Tgfbr1 by direct targeting to disrupt the TGF-β/Smad/TLR3 pathway, thus repressing renal fibrosis and the secretion of inflammatory factors in LN." (PMID 36187762, 2022). "As described ahead, let-7c from MSC-EVs ameliorated renal fibrosis in UUO model with the downregulation of Col4a1, MMP-9, TGF-β1, and TGFBR1." (PMID 31979395, 2020). "As described ahead, the transfer of let-7c from MSC-EVs ameliorated renal fibrosis in UUO model through the downregulation of Col4a1, MMP-9, TGF-β1, and TGFBR1." (PMID 31979395, 2020). "Based on the findings of the current study, the expression of ERα or TGFBR1 in the kidney can feasibly be altered to reduce the activation of the SMAD pathway, thereby reducing the production of inflammatory mediators in the context of renal fibrosis." (PMID 35281024, 2022). "Our study revealed that Glce deficiency in renal tubular cells promoted TGF‐β/Smad pathway activation predominantly associated with TGFBR1 rather than Smad3, however, inhibition of TGF‐β/Smad pathways partially relieved renal fibrosis in Glce‐/‐ mice after UUO." (PMID 40788059, 2025).